EGFR (epidermal growth factor receptor)
Diseases named in the same sentence as EGFR in open-access papers (continued):
Sharing a sentence is not in itself a finding about the gene and the disease.
cancer (continued). "These peptidomimetics were also conjugated with fluorophores and doxorubicin to target the EGFR related cancer." (PMID 33670650, 2021). "These class 3 (‘two-hit gain’) drivers include EGFR (2/3 cancer types), KRAS (4/16), and BRAF (1/6)." (PMID 34862370, 2021). "In active targeting, particular molecular modifications can be applied for targeting specifically the overexpressed surface receptors of cancer cells, such as folate receptor (FR), transferrin receptor (TfR), or Epidermal growth factor receptor (EGFR)." (PMID 34032937, 2021). "Both SF5-SAHA and SAHA suppressed EGFR expression in DU145 cells, indicating that HDAC inhibition also modulates EGFR levels in cancer cells." (PMID 34959719, 2021). "ANO1 contributes to cancer development via the promotion of oncogenic signaling, including the EGFR and CAMK pathways." (PMID 34281152, 2021). "Low sensitivity to EGFR inhibitors was confirmed in these KRAS mutated PDOs, both relative to other anti-cancer agents and relative to RAS wild-type PDOs in the reference dataset." (PMID 34496878, 2021). "Generally, high levels of ADAM17 are associated with poor cancer prognosis due to the exacerbation of EGFR signaling, but it can play additional roles in different phases of cancer progression." (PMID 33579029, 2021). "Eight vinyl sulfones from molecular docking technique were tested the inhibitory activity against EGFR-TK and cell-based assay in three cancer cell lines (A549, A431, and H1975 cell lines)." (PMID 33921332, 2021). "We investigated the cytotoxic effects of the protein dendrimers functionalized with Gmono carrying the EGFR‐specific repebody against four different cancer cell lines." (PMID 34719882, 2021). "Compound 5 and lipid conjugate of 5 (SA-5) were known to bind to the HER2 protein and inhibit EGFR dimerization in cancer cell lines." (PMID 33800723, 2021). "Together with the effects of these amplified oncogenes on the reporter data, the ERBB2/EGFR/AKT pathway appears to be a major player in ARE-mediated post-transcriptional regulation in relevant cancers." (PMID 34535639, 2021). "For example, the level of the EGFR/TGFB1 pair was overexpressed from ductal cell-fibroblast to cancer cell-fibroblast communication." (PMID 34326696, 2021). "The expression of EGFR was significantly up-regulated in cancer tissues than normal pancreatic tissues (P < 0.001)." (PMID 33937024, 2021). "Among the FASTKs interactors involved in cancer development, the best understood ones are EGFR, NTRK1 and FBXO6." (PMID 34768773, 2021). "Multiple signaling pathways involved in cancer initiation and progression, including the EGFR, VEGFR, focal adhesion and RAS signaling pathways, can be rapidly activated after the activation of AXL signaling." (PMID 34439388, 2021). "Overall, these observations allow us to exclude a context of EGFR addiction of fibroblasts and this point limits the use of anti-EGFR agents developed for cancer therapy." (PMID 33809111, 2021). "Thereby, we propose a novel mechanism of cardenolide glycoside-induced impairment of EGFR-expressing cancer cells and intend to encourage the further pharmacological exploration of these naturally-derived compounds." (PMID 34025398, 2021). "EGFR is a transmembrane receptor tyrosine kinase that can initiate several intracellular signaling pathways contributing to cancer cell proliferation, inhibition of apoptosis, invasion, metastasis and stimulation of neovascularization." (PMID 33946969, 2021). "Numerous studies have demonstrated the role of Wnt and EGFR signaling pathways in somatic stem cells and cancers." (PMID 33372708, 2021). "Dysregulation and overexpression of the EGFR-signaling pathway in several cancers ameliorate carcinogenesis, angiogenesis, cancer progression and cellular survival." (PMID 33639651, 2021).
cancer (continued). "With the recent advancements in molecular biology research, epidermal growth factor receptor-tyrosine kinase inhibitors (EGFR-TKIs) have emerged as excellent therapies for patients with EGFR-mutant cancers." (PMID 34397927, 2021). "The epidermal growth factor receptor (EGFR) family has been found to be involved in the regulation of cancer metastasis, including TNBC." (PMID 34944829, 2021). "When bound to the extracellular domain of the EGFR, cetuximab can block endogenous ligand binding and inhibit proliferation of cancer cells." (PMID 33827580, 2021). "IRDye800CW-nimotuzumab targets cancer cells, which overexpress EGFR, allowing EGFR positive tumors to be visualized during surgery." (PMID 33711962, 2021). "As a result, there has been significant interest in uncovering additional layers of EGFR signal regulation in cancer that are amenable to pharmacologic manipulation." (PMID 34610265, 2021). "Although compound 1 treatment inhibited EGFR signaling in both cancer cell lines after 24 h, inhibition was more pronounced after 48 and 72 h of treatment." (PMID 34279406, 2021). "The expression level of CD44 is positively correlated with the wild-type EGFR level in cancer tissues." (PMID 33981532, 2021). "These two IL-17A promoter SNPs can possibly be utilized as potential biomarkers in the absence of an MT EGFR in LUAD patients who smoke, as well as a cancer aggressiveness predictor for WT EGFR LUAD patients." (PMID 33802737, 2021). "The inhibition of EGFR is classified as targeted therapy as it aims at the differences between cancer and normal cells and is characterized by its high selectivity and lowered side effects." (PMID 33357002, 2021). "Other RTKIs, such as trastuzumab, which targets the HER2/ErbB2 receptor, cetuximab, erlotinib, and gefitinib, which targets the EGFR, also effectively impede cancer growth." (PMID 34769090, 2021). "More and more studies showed that EGFR is a valuable therapeutic target for many cancers, especially in LUAD." (PMID 33767988, 2021). "The expression of CD44 has been correlated with the EGFR level in a variety of cancer, and their expression is positively regulated reciprocally." (PMID 34207383, 2021). "The EGFR has a crucial role in cell differentiation and proliferation and cancer, being ARSB regulation an important target for cancer therapy." (PMID 33445445, 2021). "High levels of nuclear EGFR have been found in various types of cancers, and nuclear EGFR signaling has been involved in acquired radiation resistance and chemoresistance to cisplatin." (PMID 34199763, 2021). "Some PTs (e.g., oleanolic acid) also decrease EGFR protein expression in some different cancer types." (PMID 34681605, 2021). "Overcoming resistance mechanisms requires a deeper understanding of EGFR regulation in cancer cells." (PMID 34610265, 2021). "Epidermal growth factor receptor (EGFR), overexpressed in many types of cancer, has been proved as a high potential target for targeted cancer therapy due to its role in regulating proliferation and survival of cancer cells." (PMID 33921332, 2021). "It is well known that ligand binding and trafficking of epidermal growth factor receptor (EGFR), fibroblast growth factor-1 and VEGFR-2, the most crucial RTKs in cancer-associated angiogenesis, are affected by site-specific N-glycosylation." (PMID 34064180, 2021). "TAS0728 is an orally available, HER2-selective covalent inhibitor with high specificity for HER2 over wild-type EGFR and has exhibited potent inhibitory activity for both overexpressed/amplified HER2 and mutated HER2 in cancer cells." (PMID 33774767, 2021). "The downstream signaling cascades of EGFR, their critical protein interaction partners and cancer promoting effects have recently been reviewed." (PMID 33469705, 2021). "The regulation of autophagy by EGFR and its clinical impacts are indicated in various types of cancer." (PMID 34830108, 2021).
cancer (continued). "CNAs of kinases, including ERBB2, FGFR1, and EGFR, were correlated with overexpressed proteins in substantial fractions of the same cancer types." (PMID 34552204, 2021). "In the present study, a new therapeutic strategy for treating EGFR-TKI-resistant NSCLC that focuses on cancer metabolism is proposed and the pharmacological efficacy of phenformin, a biguanide agent was elucidated." (PMID 34367462, 2021). "It is reasonable that cancer cells with de novo resistant mechanisms (such as the T790M mutation in H1975 cells and the PTEN null in H1650 cells) exhibit inherent resistance to EGFR TKIs." (PMID 34202566, 2021). "Phosphatase and tensin homologue (PTEN) is an important cancer-suppressor gene and one of EGFR downstream cascade members." (PMID 33906293, 2021). "Most recently, a Bifidobacterium clone, APS002, has been established to secrete diabodies against EGFR/HER3 and CD3 and redirect T cells to EGFR/HER3-positive cancer cells." (PMID 34204302, 2021). "TMEM52B suppression reduces E-cadherin stability to produce soluble E-cadherin and enhances the activation and internalization of EGFR and its downstream signaling activity, leading to cancer cell invasion and survival." (PMID 33641663, 2021). "The EGFR is necessary for cell development and homeostasis, the overexpression of which is common in many malignant tumors, and is a driver of tumorigenesis in various cancers, including NPC." (PMID 34578147, 2021). "Self-sufficiency of growth signals and constitutive activation of mitogenic pathways is a hallmark of cancer, and malignant tumours often show deregulation of tyrosine kinases that include growth factor receptors such as KIT, EGFR, PDGFR, and VEGFR." (PMID 34822659, 2021). "Again, highly selective cancer cell death was achieved by SPIONs/gold hybrids engineenered with epidermal growth factor receptor." (PMID 34064173, 2021). "Some informative studies report the efficacy of EGFR-targeted therapies on cancer progression using EGFR tyrosine kinase inhibitors (TKIs) or EGFR-neutralizing antibodies." (PMID 32901097, 2021). "Prior evidence has implicated EGFR/RON crosstalk in the modulation of important cellular responses, notably migration and invasiveness in cancer." (PMID 34821550, 2021). "The deregulation of EGFR has been observed in multiple types of cancers, including NSCLC, while frequent EGFR protein overexpression was observed in NSCLC and COPD." (PMID 34635059, 2021). "Even though targeted therapies are available for cancers expressing oncogenic epidermal growth receptor (EGFR) and (or) human EGFR2 (HER2), acquired or intrinsic resistance often confounds therapy success." (PMID 34074257, 2021). "Abundance of certain proteins such as epidermal growth factor receptor (EGFR) and their growth factors on cancer cells is in part responsible for their uncontrolled growth." (PMID 33535661, 2021). "It is also found to augment inhibitory effect of other EGFR inhibitors such as Erlotinib and Lapatinib in cancer treatment." (PMID 34944593, 2021). "An additional protein or antibody is bound to the virus, making it prone to connect to the EGFR of the cancer cell." (PMID 34063231, 2021). "In particular, RAS clones raised in blood during EGFR blockade decline after the withdrawal of anti-EGFR antibodies, therefore restoring the drug sensitivity of cancer cells and providing a rationale for anti-EGFR retreatment." (PMID 33535557, 2021). "Aguilera produced multifunctional tannic acid nanoparticles with an extremely high entrapment efficiency of the active principle and targeted to EGFR, which were only toxic for the cancer cells." (PMID 33499388, 2021). "On the other hand, it has been previously reported that EGF stimulation in cancer cells can promote both the homodimerization of EGFR and heterodimerization of EGFR with human epidermal growth factor receptor 2 (HER2)/Erb-B2 receptor tyrosine kinase 2 (ErbB2)." (PMID 33705793, 2021).
cancer (continued). "In summary, our study showed that 13f has potent anti-cancer activities including antiproliferation, clonogenic ability and migration through the modulation of EGFR signaling pathway in CCA for the first time." (PMID 33639651, 2021). "EGFR is an important molecular marker and target for many types of cancers including PC, breast cancer, glioblastomas, and colorectal cancer." (PMID 34577541, 2021). "Previously we showed that expression of PD-L1 in PDA cancer cells is regulated by epidermal growth factor receptor (EGFR)/MAPK signaling cascade." (PMID 34290984, 2021). "In fact, in paradigms such as EGFR-mutant NSCLC, EGFR inhibition has limited success in patients whose cancers cannot undergo robust apoptosis." (PMID 33589591, 2021). "Another classical signaling pathway targeted by kinase inhibitors for cancer treatment is the epidermal growth factor receptor (EGFR) pathway." (PMID 33513872, 2021). "This study obtained samples from patients with diverse genetic drivers of their cancers, including EGFR, ALK and KRAS." (PMID 34677350, 2021). "A wide range of cancer diseases appear to have EGFR highly expressed, and in some of them, such as HNC and colon cancer, are highly reliant on this signaling pathway for their survival." (PMID 34681918, 2021). "The activated signaling pathways avoid the damage of TKI to cells, promote proliferation of cancer cells, and ultimately lead to the resistance of patients with cancer to EGFR‐TKIs." (PMID 34555268, 2021). "Given the frequency of EGFR activation in cancer, additional tyrosine kinase inhibitors, TKIs, directed at the cytoplasmic domain of EGFR have also been developed." (PMID 33809714, 2021). "The NSCLC patients with wild‐type EGFR‐ or mutant EGFR‐specific miRNAs validated in this study demonstrate that exosomes are actively excreted from cancer cells and that their specific miRNA components depend on the cells from which they originated." (PMID 33682961, 2021). "Three compounds, 6b, 7j and 9a, presented excellent inhibitory activity against gefitinib-resistant NSCLC cell line H1975 harboring EGFRL858R/T790M, indicating their potential against EGFR mutant cancer." (PMID 33803355, 2021). "Despite the fact that EGFR has been mainly studied in the field of cancer, increasing studies have discovered diverse roles in pathogenic bacterial infections, such as regulating bacterial invasion, inflammation, and apoptosis." (PMID 33985523, 2021). "In particular, several studies have been conducted for selecting peptide ligands of EGFR as promising tools for targeting overexpressed EGFR receptors in different cancer cell types." (PMID 33918836, 2021). "Necitumumab is the first anti-EGFR therapeutic antibody that is indicated only in squamous NSCLC patients whose cancer is positive for EGFR by immunohistochemistry." (PMID 33535661, 2021). "EGFR is a major signal transducer of mitogens in cancer pathogenesis and the progression, upstream, of mTOR and is an important target in anticancer therapy." (PMID 33925400, 2021). "A variety of targeted therapies that block the EGF/EGFR pathway have proven to be an effective therapy for cancer." (PMID 34804932, 2021). "The epidermal growth factor receptor (EGFR) family has been demonstrated to strongly affect EMT process in many types of cancer, including pancreatic." (PMID 33937024, 2021). "Currently, first- to third-generation EGFR-TKIs are in clinical use for the treatment of different types of cancers." (PMID 34771085, 2021). "Since heterointeractions between EGFR and other RTKs play an essential role in cancers, many papers have tried to decode these heterointeractions." (PMID 33603128, 2021). "These two patients were diagnosed as having cervical lymph node metastasis, thereby supporting the proposed role of the EGFR+ EVs in cancer progression." (PMID 33558596, 2021). "Elevated EREG in various cancers mainly activates EGFR signaling pathways and promotes cancer progression." (PMID 34884633, 2021).
cancer (continued). "EGF/EGFR signaling is hyperactive in a broad array of human cancers including malignant breast cancer, skin tumor, non-small cell lung cancer (NSCLC), colorectal cancer, and pancreatic cancer." (PMID 34433808, 2021). "This study laid the foundation for the development of an anti-EGFR probody, the first probody to treat cancer cells." (PMID 33391977, 2021). "Mutations and high‐level amplifications of cancer‐critical genes, the latter including ERBB2 and EGFR, were predominantly homogeneous within patients." (PMID 33325154, 2021). "Elevated EREG expression levels appear to be a potential predictive biomarker of anti-EGFR therapies in several cancer types." (PMID 34884633, 2021). "Since RAC1 was increasingly translocated to the nucleus in cancer cells, we subsequently examined the spatio-temporal coordination of EGFR with RAC1." (PMID 34741044, 2021). "EGFR vIII, in combination with its unique extracellular domain (which lacks exons 2–7), possesses cancer-specific expression that fascinates many neuro-oncology researches." (PMID 34582442, 2021). "We also found significant enrichment for known cancer driver genes from the COSMIC (Catalogue Of Somatic Mutations In Cancer) database in our predicted causal genes list, such as CDK4, EGFR, PTK6, and CCND1 (29/264; Fisher adjusted p < 0.01)." (PMID 34010657, 2021). "In this paper we investigated the crosstalk between integrin β4 and the EGFR in the activation of cancer promoting signaling pathways in a variety of cell lines." (PMID 33883672, 2021). "This offers great potential for a combination of anti-EGFR IgG1-antibodies with immune checkpoint inhibitors in a multimodal setting to amplify the anti-cancer immune response, and to increase response rates and the duration of the response." (PMID 33718186, 2021). "In summary, multiple reports have provided evidence of the relationship between the activation of inflammatory cytokines and the resistance of cancer cells to EGFR-TKIs." (PMID 33466795, 2021). "Another antibody clone, 528, is an antagonistic anti-EGFR antibody, which has been the focus of our antibody engineering studies to develop cancer drugs." (PMID 33707468, 2021). "Progesterone receptor membrane component 1 (PGRMC1) and epidermal growth factor receptor (EGFR) are highly expressed in various cancers." (PMID 34069911, 2021). "As a proof-of-concept, anti-EGFR-AffiBeads were fabricated and applied to capture and detect human lung A549 cancer cell-derived EGFR-positive exosomes using flow cytometry and fluorescent microscopy." (PMID 34769444, 2021). "cfDNA-based EGFR mutation tests have been used in advanced NSCLC to establish a prognosis and assess resistance to anti-cancer agents." (PMID 33863951, 2021). "It has been described that HNSCC cell lines express higher EGFR levels than what is generally found in the cancer tissue." (PMID 36405501, 2021). "While EGFR expression normally is found between 40 000 to 100 000 receptors/cell (depending on the tissue type), overexpression of EGFR is seen in a majority of cancers, with up to 2 000 000 receptors/cancer cell." (PMID 34557197, 2021). "Our study also focused on anti-cancer role of Gliclazide, thus H1299 and A549lung cancer cell lines, both of which are with wild type EGFR, were selected for experimental in vitro." (PMID 34249701, 2021). "Although the functions of GPCs have been assigned in different tumors, including lung, colon, and breast cancers, esophageal squamous cell carcinoma, and pancreatic ductal adenocarcinoma, their interaction with EGFR in NSCLC remains yet to be explored." (PMID 34976811, 2021). "Data showed that hyper-accessible regions in ESCC cells contained genes related with cancer hallmarks, such as epidermal growth factor receptor (EGFR)." (PMID 34722266, 2021).